TF (transferrin)
Diseases named in the same sentence as TF in open-access papers (continued):
Sharing a sentence is not in itself a finding about the gene and the disease.
breast carcinoma (continued). "Paclitaxel (PTX), transferrin,and antimiR-135b were conjugated with AuNPs and their uptake by mousetumor cells in an induced breast cancer model was investigated." (PMID 39130536, 2024). "Previous studies on the use of transferrin conjugates in breast cancer considered primary breast tumors." (PMID 38117806, 2023). "Further, in vitro and in vivo evidence suggests that deferoxamine (DFO), an FDA-approved iron chelator under investigation for the treatment of breast cancer, can enhance uptake of transferrin conjugates by metastatic breast cancer." (PMID 38117806, 2023). "Since then, preclinical models or early-stage clinical studies have addressed the potential of conjugating transferrin to chemotherapeutics, drug-carrying nanoparticles, and optical or radioactive tracers to target breast cancer." (PMID 38117806, 2023). "Conjugation of transferrin (Tf) to imaging or nanotherapeutic agents is a promising strategy to target breast cancer." (PMID 38117806, 2023). "We show a correlation between ZNF469 and breast cancer metastasis-related TF expression from RNA sequencing (RNA-seq) data of breast cancer in TCGA database." (PMID 37736108, 2023). "Transferrin was identified as a key factor for breast cancer cell survival about 40 years ago, and TfR was shown to be upregulated in breast cancer relative to normal breast or fibromas." (PMID 38117806, 2023). "Fluorophore-conjugated transferrin iron chelator deferoxamine (DFO) enhanced TfR uptake in human breast cancer cells in vitro and proved transferrin localization at metastatic sites and correlation of tumor burden relative to untreated tumor mice." (PMID 38117806, 2023). "The adaptive response to iron scarcity is the overexpression of TfR, observed in breast cancer experiments, and previously used to increase the uptake of transferrin conjugates in vitro in glioma or leukemia cells." (PMID 38117806, 2023). "For instance, in breast cancer (BC) cell lines, miR-19 directly inhibits TF expression, and miR-19a inhibits TF expression in colon cancer (CC) cells." (PMID 37958279, 2023). "Treatment with DFO increased the uptake of transferrin conjugates by breast cancer cells in vitro and in a mouse model of metastatic breast cancer." (PMID 38117806, 2023). "In vivo experiment showed that TF was a growth factor in some tumors, such as leukemia, breast cancer and pituitary tumor." (PMID 36845727, 2023). "The GATA2 TF is related to kidney and breast cancer-related pathway when the higher expression pattern of YY1 TFs increases the tumour size and higher TNM stage." (PMID 36016137, 2022). "A significant number of studies show the importance of TACAs in breast cancer such as Thomsen-nouvelle antigen (Tn), sialyl-Thomsen-nouvelle antigen (sTn), Thomsen–Friedenreich antigen (TF) and sialyl-LewisX (sLeX)." (PMID 36552021, 2022). "In this study, we evaluated in situ the expression of TF antigen, a truncated O-glycan that has been reported to be expressed in different tumors, such as ovarian cancer, breast cancer, CRC, and acute lymphoblastic leukemia (T-cell)." (PMID 33572915, 2021). "Seven cell cycle-related genes have been identified with unfavorable prognosis of their TF-miRNA-mRNA regulatory network in breast cancer." (PMID 34354775, 2021). "In this regard, previous reports have showed that DFO IV infusion rapidly clears around one third of the non-transferrin-bound iron in the blood and reduces intracellular labile iron stores in breast cancer cells." (PMID 34439518, 2021). "This study established a novel nanoparticle based on a transferrin-modified chemotherapy nanocomplex and thermo-sensitive liposomes for breast cancer treatment." (PMID 34959271, 2021). "Another recent study investigated the possibility of targeting cancer cell TF expression with nanoparticle-mediated delivery of siRNA to the site of metastasis in a breast cancer mouse model." (PMID 33777033, 2021).
breast carcinoma (continued). "Based upon our results, we can suggest that prepared transferrin-conjugated solid lipid nanoparticles (SLNs) has significant potential to deliver the Tamoxifen citrate in the treatment of breast cancer with improved therapeutic activities." (PMID 33329007, 2020). "High levels of TF expression have been observed on 4T1 cancer cells in a murine breast cancer model." (PMID 32191918, 2020). "In the present study, transferrin-conjugated solid lipid nanoparticles (SLNs) were successfully prepared to enhance the active targeting of tamoxifen citrate in breast cancer." (PMID 33329007, 2020). "Growth of the breast cancer cells is shown to be dependent on iron and transferrin in the culture medium." (PMID 33292585, 2020). "While reaffirming the high contribution (and thus high potential of biological function) of the TA and TF genes to breast cancer ceRNA networks, we further found the high contribution of HK genes." (PMID 32411683, 2020). "Systemic inflammatory markers such as C-reactive protein (CRP), fibrinogen, ferritin, albumin, transferrin, and blood leukocyte components like neutrophils and lymphocytes are associated with prognosis of RCC, colorectal, and breast cancers." (PMID 29541572, 2018). "BRCA-Pathway stores and utilizes data such as TCGA breast cancer data, breast cancer subtype by PAM50, TF-TG regulation data, Hallmark gene sets, driver gene list and KEGG pathway data." (PMID 29504910, 2018). "Changes in the paramagnetic centers can serve as a biomarker of breast cancer development because they reflect functional changes of ceruloplasmin and transferrin." (PMID 28849262, 2017). "Applications in human breast cancer and the hiPSC-derived CM development demonstrate consistency between the identified TF gene regulation and the previous experiments." (PMID 29051499, 2017). "Ceruloplasmin and transferrin are proteins which play a potential role in the process of breast cancer development." (PMID 28849262, 2017). "For example, specific cell surface receptors, such as transferrin, or folate receptors are overexpressed on cancer cells, including glioblastoma and breast cancer, among other types of cancer." (PMID 29036899, 2017). "In another study, transferrin-mediated SLNs were prepared to increase photostability and anticancer activity of curcumin against breast cancer cells in vitro." (PMID 24995293, 2014). "Results indicated the potential of transferrin-mediated SLNs in enhancing the anticancer effect of curcumin in breast cancer cells in vitro." (PMID 24995293, 2014). "In a breast cancer cell line, TF activity and TF mRNA was reduced by about a third by captopril exposure in vitro." (PMID 25211298, 2014). "The measurement of TF antigen in NAF from 23 women with biopsy proven breast cancer using the galactose oxidase-Schiff (GOS) reaction was reported in 2004." (PMID 22296682, 2012). "Our results are in agreement with the previous study showing that TfR1 antibody, which specifically blocks the binding region of TfR1 for transferrin, inhibited breast cancer cell proliferation and increased VEGF formation." (PMID 20723262, 2010). "Studies examining the relationship between serum iron parameters (serum iron, ferritin, transferrin saturation, and total iron-binding capacity) and breast carcinoma subtypes, histopathological grading, and molecular immunophenotypes were analyzed for inclusion." (PMID 41896371, 2026). "Interestingly, the iron homeostasis maintained by transferrin and its receptor has been thoroughly studied in breast cancer treated with artesunate." (PMID 40758729, 2025). "This complexity makes it more difficult to study FOX TF and its related breast cancer treatment." (PMID 40003882, 2025). "A meta-analysis of 11 prospective studies investigating the associations between iron markers and breast cancer risk found a 22% increased risk associated with serum/plasma iron, but not for ferritin, transferrin saturation, or total iron-binding capacity." (PMID 39246326, 2024).
breast carcinoma (continued). "In breast cancer cases, dysregulation of iron-binding proteins, such as transferrin, which facilitates the delivery of ferric ions into cells, and iron-transporting proteins, like ferroportin, which is responsible for exporting iron out of cells, is frequently observed." (PMID 39867656, 2024). "In order to translate the use of DFO to improve delivery of transferrin conjugates to breast cancer in vivo, two potential limitations needed to be addressed: safety of the treatment, and effects on tumor growth that may add confounding factors." (PMID 38117806, 2023). "Transferrin targeting for breast cancer has been developed into promising technologies." (PMID 38117806, 2023). "In addition, computational prediction indicated that DPP4 was down-regulated in breast cancer, TF was down-regulated in other tumors and ZFP69B was up-regulated in other tumors." (PMID 36568247, 2022). "Transferrin levels were also found to be altered in breast cancer cases." (PMID 35888054, 2022). "In combination with TF, uPA could predict breast cancer in both pre- and post-menopausal women with 84-92% accuracy." (PMID 32992445, 2020). "Similarly, the multivariate analysis demonstrated that tumour TF expression was an independent prognostic indicator for overall survival in breast cancer patients." (PMID 33316933, 2020). "The overexpression of TF can increase the activity of breast cancer stem cells in vitro." (PMID 33665205, 2020). "Overall, proposed study highlights that transferrin engineered nanocarriers could enhance the therapeutic response of nanomedicines for breast cancer treatment." (PMID 33329007, 2020). "In this regard, the attained AS/Transferrin-HMCuS NPs facilitated local drug accumulation and retention, targeted to breast cancer MCF-7 cells specially via TfR-mediated endocytosis, combined chemotherapy-phototherapy synergistically, and eventually improved the anticancer effect." (PMID 29755355, 2018). "Second, six genes, CHI3L1, CXCL8, FOXC2, SERPINE1, SFRP2, and TF, which are grouped within the highest enrichment GO term, “positive regulation of angiogenesis”, have been reported to play roles in various cancer processes, including breast cancer." (PMID 30205506, 2018). "That is, we investigated whether the differentially methylated TFBS in promoter CpGI shore regions among breast cancer subtypes potentially give influence to expression of downstream genes that TF regulate." (PMID 28155687, 2016). "ER-alpha is a ligand-activated TF known to play important role in breast cancer development." (PMID 21912677, 2011). "We propose that SDC3 may regulate the activity of the proto-oncogene tyrosine-protein kinase Src (SRC) in the context of the TF pathway, as well as other genes involved in crucial breast cancer signaling pathways, thereby affecting human breast cancer cell behavior." (PMID 41148827, 2025). "However, breast cancer risk was associated with increased serum/plasma iron levels but not ferritin or transferrin saturation." (PMID 39246326, 2024). "For instance, the most strongly associated TF with the AP-1 motif in kidney cancer is RUNX1, while in breast cancer it is FOXA1, suggesting that many of the AP-1 motif-containing sites may require AP-1 dependent de-repression along with positive RUNX1/FOXA activation." (PMID 25994056, 2015). "CAR-NK cells targeting CD44v6, HER2, TF, B7-H6, EGFR, and PD-L1 have been successfully used for treating different types of breast cancer." (PMID 38680498, 2024). "Triple negative breast cancer cell line MDA-MB-231 has previously been shown to express TF, therefore we tested the CAR T cell capacity to recognise endogenous levels of TF." (PMID 39105809, 2024). "The TF protein MSX1 has been identified as a prognostic marker for several conditions, including colorectal cancer (CRC), breast cancer, and endometriosis." (PMID 39024368, 2024).
breast carcinoma (continued). "Although CAR-NK cells targeting CD44v6, HER2, TF, B7-H6, EGFR, and PD-L1 have made great progress in breast cancer, developing targets for CAR-NK cells in breast cancer has great research potential." (PMID 38680498, 2024). "Among the TFs, the Alzheimer’s disease, basal-like breast cancer (BLBC), and tissue invasion are highly related with FOXC1 TF." (PMID 36016137, 2022). "Transferrin decorated nanoparticles to deliver DOX and CUR for the treatment of breast cancer were investigated in this research." (PMID 34960948, 2021). "Transferrin, TFRC and SLC11A2, which are responsible for importing iron into cells, are also expressed at higher levels in breast carcinoma than normal tissues, while the iron exporter SLC4A1 exhibited lower expression." (PMID 33292585, 2020). "The transferrin conjugated micelles, compared with the non-transferrin functionalized theranostic micelles, showed higher cellular uptake, higher cytotoxicity in MDA-MB-231-luc breast cancer cells." (PMID 29755355, 2018). "Hence, measuring soluble FTN and TF in NAF may help the early identification of women with increased breast cancer risk, even though these proteins are not expressed by local breast tissues." (PMID 29344009, 2018). "Although FOX TF is rarely directly used as a drug target, it is not uncommon to study the treatment of breast cancer by acting upstream of FOX and regulating the expression of FOX." (PMID 40003882, 2025). "This study sought to functionalize RNVs with a diverse array of tumor-targeting ligands – cRGD, transferrin (TRF), folic acid (FA), GE11, and RVG29 – and to systematically compare their tumor-homing efficiency, biodistribution, and biosafety in a breast cancer model." (PMID 41216197, 2025). "Similar findings were also reported by Zheng and colleagues, who demonstrated that transferrin-conjugated lipid-coated PLGA nanoparticles entrapping calcein exhibited more effective uptake by SKBR-3 breast cancer cells than their non-targeted counterparts." (PMID 38004621, 2023). "As main protein-carriers, Hcs are widely used for TACA-based cancer vaccine constructions in several tumor models and clinical trials: Globo-H-KLH conjugate vaccine for breast cancer; Globo-H-GM2-sTn-TF-Tn-KLH conjugate vaccine for ovarian cancer; and GM2-KLH conjugate for melanoma treatment." (PMID 35736195, 2022). "Authors hypothesized that these proteins on BrCr-coated NPs interacted with transferrin and HDL receptors known to be overexpressed in breast cancer." (PMID 36546919, 2022). "Previously, depletion of TF gene or treatment with SC1 in TF-high expressing pancreatic or breast cancer cells did not acutely block cell proliferation in vitro, but elicited in vivo efficacy in nude mice xenograft tumor model." (PMID 32923403, 2020). "Among serum/plasma indicators of body iron status, the highest (vs. lowest) level of iron, but not ferritin, transferrin, TIBC, or TSAT, also showed a statistically significant association with increased breast cancer risk (22%)." (PMID 31170936, 2019). "As expected, some proteins from serum such as transferrin adsorbed on PAV-AuNPs could strongly and selectively interact with breast cancer cells." (PMID 29996877, 2018). "Cancer cells contain high levels of transferrin (TF) and ferritin (FTN), as well as higher expression of TF receptors compared to normal cells, suggesting proteins involved in Fe metabolism play important role in the proliferation of breast cancer cells." (PMID 29344009, 2018). "We are currently studying Rivaroxaban, a DOAC licensed for the prophylaxis and treatment of VTE that is an inhibitor of Factor Xa, thereby inhibiting the TF-Factor VIIa-Factor Xa complex, in a Phase II trial of early breast cancer patients (TIP Trial, EudraCT No.: 2014–004909-33)." (PMID 31473984, 2020).
breast carcinoma (continued). "Of the 25 NAF samples from breasts with cancer, 19 samples had TF and 20 samples had Tn, whereas only one of the 25 NAF samples from breasts without cancer contained Tn and neither TF nor Tn was detected in the rest, indicating that TF and Tn can be used as detection biomarkers for breast cancer." (PMID 32992445, 2020). "Similarly, for early breast cancer, the best three k-gene discriminators are {GPR109B, PCOLCE2, PCSK5}, {PCSK5+COL10A1, FERMT2+SPINT2, MAOA+IGJ}, {COL1A1+PCSK5+TF, GPX3+COL1A1+SPINT2, GPX3+FAP+TMEM97}, and {RRM2+COL1A1+GPR109B+IGJ, RRM2+COL1A1+GPR109B+IGJ, RRM2+COL1A1+GPR109B+SPINT2}, respectively." (PMID 21060876, 2010). "In addition, the possible ferroptosis mechanisms of CDKN2A, PSAT1, SLC7A11, LAMP2, CAV1, and HMGB1 in TNBC and ASNS, ZFP69B, ELAVL1, TF, HELLS, and DPP4 in breast cancer have not been reported." (PMID 36568247, 2022).